ANXA6 (annexin A6)
Diseases named in the same sentence as ANXA6 in open-access papers (continued):
Sharing a sentence is not in itself a finding about the gene and the disease.
tumor (continued). "The anti-tumor effect of AnxA6 in xenograft or orthotopic mouse models was evaluated." (PMID 38566133, 2024). "Moreover, we also validated EGFR/ERK signaling changes between AnxA6 and AnxA6K299R-expressing tumor tissues from A431-xenograft nude mice." (PMID 37528485, 2023). "ANXA6 may affect the growth and invasion of a variety of tumor cells by affecting LE/Lys-Chol transport channels." (PMID 37129645, 2023). "Association of ANXA6 polymorphisms and HNC risk stratified by tumor sites." (PMID 36998449, 2023). "Moreover, AnxA6 knockdown or the K299 mutant AnxA6K299R conferred AnxA6 inability to suppress tumor progression, resulting in drug resistance to gefitinib in epithelial cancer cells." (PMID 37528485, 2023). "Consistent with the in vitro experiments, ANXA6 KD inhibited tumor growth and metastasis in vivo." (PMID 37138336, 2023). "However, the specific mechanism of action of ANXA6 in different tumors depends on the corresponding tumor type and cellular characteristics." (PMID 37129645, 2023). "Previous studies have indicated that in certain tumor types and stages, ANXA6 may either suppress or promote tumorigenesis owing to its diverse functions." (PMID 37138336, 2023). "ANXA6 is a scaffold protein that participates in tumor pathogenesis and autophagy regulation; however, how ANXA6 affects autophagy and LM in HNSCC cells remains unknown." (PMID 37138336, 2023). "More specifically, due to its unique structure, ANXA6 may act as either a tumour suppressor or a tumour promoter depending on the type and stage of cancer." (PMID 36936694, 2023). "For other tumor types, the silencing of ANXA6 could reduce the aggressiveness of pancreatic and lung squamous carcinoma." (PMID 37129645, 2023). "In an animal study, ANXA6 KD inhibited tumor proliferation and lymphatic dissemination." (PMID 37138336, 2023). "In addition, ANXA6 has emerged as a potential biomarker in ovarian cancer, since it was found significantly upregulated in tumor tissue samples, particularly in stages II-IV compared to health tissue." (PMID 36247003, 2022). "Furthermore, the reduced expression of AnxA6 has been shown to promote rapid tumor growth and affect several aspects of energy metabolism including adipogenesis), and gluconeogenesis." (PMID 35267416, 2022). "We have previously shown that fatty acid-binding protein 4 (FABP4) was significantly upregulated following AnxA6 downregulation in BT-549 cells, and that this was consistent with increased cell proliferation and early onset and rapid xenograft tumor growth in mice." (PMID 35267416, 2022). "Paclitaxel and adriamycin could be said to be two completely different chemotherapy drugs, both of which promoted tumor metastasis through exosome and ANXA6, perhaps this effect of chemotherapy in promoting metastasis was widespread." (PMID 35719975, 2022). "Hence, overexpression and gene knockdown studies in cell culture and animal models, as well as expression patterns in patient cohorts, identified AnxA6 to exhibit tumor suppressor activities." (PMID 35806209, 2022). "Chemotherapy-induced tumour EVs promote proinflammatory endothelial cell activation, and chemokine (C–C motif) ligand 2 (CCL2) upregulation via a mechanism involving EV-associated annexin-A6 (ANXA6) translocation to the lung endothelium." (PMID 36096820, 2022). "Indeed, studies in humans demonstrated that lapatinib is useful in patients with triple-negative breast tumors, by activating NF-kB and the anti-apoptotic Bcl-2 protein, sensitizing tumor cells to the annexin A6 upregulation and inducing apoptosis." (PMID 33800900, 2021). "Besides data from cell culture models or expression analysis of patient cohorts, several studies in recent years examined roles for AnxA6 in tumour growth and progression in vivo." (PMID 33810523, 2021). "Our data provided evidence that the presence of ANXA6 in blood samples before gemcitabine-based chemotherapy may be a reliable predictor of tumor cell responsiveness to treatment." (PMID 34238922, 2021).
tumor (continued). "Here, we highlight the current developments on the potential tumor suppressor and proinvasive roles of AnxA6 in TNBC and other cancers, and how this may be relevant for TNBC diagnosis and prognosis." (PMID 32784650, 2020). "Our results reveal an important mechanism for ANXA6 in tumor suppression and autophagy regulation." (PMID 33135350, 2020). "Initial evidence suggesting that AnxA6 levels may influence drug sensitivity and possibly the development of drug resistance is based on the concept that AnxA6 exhibits tumor suppressor activity." (PMID 32784650, 2020). "Even though these assays are far from being reliable, it seems feasible that detection of AnxA6 in normal or benign tissues versus malignant tumors may be a reliable indicator of tumor progression and/or malignancy." (PMID 32784650, 2020). "Accumulating evidence now suggests that AnxA6 may also affect the growth of tumor cells by modulating glucose and lipid metabolism, with consequences in cellular energy status and consumption." (PMID 32784650, 2020). "Additionally, and although loss of AnxA6 and the accompanying dysregulation of Ca2+ influx supported rapid growth of xenograft tumors, overexpression of AnxA6 not only supported increased cell motility but also attenuated xenograft tumor growth." (PMID 30719209, 2019). "The diminished cellular levels of RasGRF2 in AnxA6 expressing cells and the associated decrease in the activation of Ras and ERK1/2 as well as reduced tumor growth are consistent with the inhibition of the growth of AnxA6 expressing tumor cells." (PMID 30719209, 2019). "To test this we carried out GTPase activation assays to determine whether altered AnxA6 expression affected the effector functions of RasGRF2 i.e. activation of Ras proteins to promote tumor cell growth and inhibition of Cdc42 to inhibit tumor cell motility." (PMID 30719209, 2019). "This suggests that AnxA6 is a tumor suppressor and a metastasis promoting factor." (PMID 24354805, 2013). "In the present study we showed that AnxA6 is indeed required for the sustained localization of activated EGFR on the surface of invasive tumor cells and that this contributes to persistent activation of downstream effectors that drive motility and invasiveness of the cells." (PMID 24354805, 2013). "Finally, we evaluated AnxA6 anti-tumor effect in xenograft nude mouse model." (PMID 37528485, 2023). "Therefore, the interaction of ANXA6 with the EGFR may be a potential mechanism for tumor drug resistance." (PMID 37129645, 2023). "Interestingly, increased PDAC aggressiveness was associated with the tumor cell-mediated uptake of CAF-derived ANXA6+ EVs carrying the ANXA6/LRP1/TSP1 complex, whereas the depletion of ANXA6 in CAFs impaired the complex formation and subsequently the occurrence of metastasis." (PMID 36614326, 2023). "Several pharmacological agents have also been shown to induce the expression of AnxA6 but the effect of hypoxia, a major factor in the tumor microenvironment, on the expression of this gene and consequently, the response of TNBC cells to targeted therapies remain unclear." (PMID 36230969, 2022). "Hence, ANXA6 may function as a tumor suppressor or tumor promoter, depending on the cancer subtype and degree of malignancy." (PMID 36247003, 2022). "Thus, tumor cells with low AnxA6 expression levels are expected to respond more rapidly to therapeutic interventions, while cells with higher AnxA6 levels may be more refractory to treatment." (PMID 32784650, 2020). "Finally, membrane-translocated AnxA6 may also facilitate membrane repair of tumor cells especially following extracellular insults." (PMID 32784650, 2020). "Furthermore, stable AnxA6 expression in A431 xenografts also reduced tumor growth in vivo." (PMID 32784650, 2020).
tumor (continued). "Over the last several years, annexin A6 (AnxA6), a calcium-dependent membrane binding protein, has been shown to play a major role in the differentiation of chondrocytes, migration of neural crest cells, growth, adhesion and motility of tumor cells and in membrane repair." (PMID 30719209, 2019). "Since Ca2+ influx is modulated by AnxA6 and RasGRF2 promotes cell growth and inhibits cell motility, our data suggest that high RasGRF2/low AnxA6 may define rapid tumor growth and poor invasiveness while low RasGRF2/high AnxA6 may be associated with invasive but slow growing tumors." (PMID 30719209, 2019). "Together these data not only support the tumor suppressor function of AnxA6 but also suggest that the effector functions of RasGRF2, cell growth via Ras activation and inhibition of cell motility via Cdc42, are important in AnxA6 modulated tumor growth and cell motility." (PMID 30719209, 2019). "Although the cellular cues that provoke down-regulation of AnxA6 in solid rumors and the role of other RasGEFs remain unknown, this study underscores the importance of AnxA6 modulated Ca2+ influx and the effector functions of RasGRF2 in AnxA6 mediated tumor growth and/or motility." (PMID 30719209, 2019). "Also, annexin A6 has an inhibitory effect on Ras/MAPK signalling which implies that it could function as a tumor suppressor." (PMID 26060582, 2015). "However, as a scaffolding protein, AnxA6 may stabilize activated cell-surface receptors to promote cellular processes such as tumor cell motility and invasiveness." (PMID 24354805, 2013). "Together, these data suggest that while stabilization of activated EGFR by AnxA6 may be important in the dissemination of invasive tumor cells, EGFR activity is dispensable in the enhanced proliferation of cells that either lack, or express low levels of AnxA6." (PMID 24354805, 2013). "Another protein, known as exosomal annexin A6 (AnxA6), has been found to be highly expressed in gemcitabine‐resistant TNBC cells and induces tumour resistance through the inhibition of EGFR ubiquitination and degradation." (PMID 40032646, 2025). "Our data also confirms our previous report suggesting that the reciprocal expression of AnxA6 and Ki67 in TNBC tumor biopsies can delineate AnxA6-high/Ki67-low invasive TNBC cells from AnxA6-low/Ki67-high proliferative tumor cells." (PMID 41279138, 2025). "AnxA6 deSUMOylation contributes to HCC progression and EMT phenotype, and the combination of AnxA6 and SENP1 is a better tumor biomarker for diagnosis of HCC grade malignancy and prognosis." (PMID 38566133, 2024). "In the current study, we have confirmed that AnxA6 is major modified by SUMO1 at K579 residue which plays a key function in HCC cell migration and tumor growth." (PMID 38566133, 2024). "Formation of the Annexin A6/LDL receptor-related protein 1/thrombospondin 1 (ANXA6, SE = 3.9/LRP1, SE = 2.5/THBS1, SE = 6.8) complex was restricted to CAFs and required physio-pathologic culture conditions that improved tumor cell survival and migration." (PMID 38892190, 2024). "Aside from ANXA2 and ANXA6, other ANXA family proteins can be used as markers of tumour occurrence and development as they affect a variety of signal pathways, such as cancer cell invasion, migration, apoptosis and autophagy." (PMID 36936694, 2023). "In this study, our results support that AnxA6 SUMOylation at K299 residue facilitates the binding of PKCα to EGFR and subsequently enhances its tumor-suppressor activity in vitro and in vivo." (PMID 37528485, 2023). "We subcutaneously injected A431 cells, which stably expressing either AnxA6 or AnxA6K299R, into BABL/c mice to observe tumor growth." (PMID 37528485, 2023). "The exceptions are ANXA5, ANXA6, ANXA10 and ANXA11, which play roles in several tumour types, while other ANXA members promote tumour cell proliferation." (PMID 36936694, 2023).
tumor (continued). "This suggests that glucose uptake and glycolysis are upregulated in response to hypoxia-induced expression of AnxA6, and that metabolic adaptation and/or plasticity of TNBC cells during tumor hypoxia are AnxA6 dependent." (PMID 36230969, 2022). "Conversely, the expression levels of ANXA6, ANXA7, and ANXA11 were significantly reduced in tumor tissues." (PMID 34484309, 2021). "They highlighted the potential tumor suppressor function in TNBC progression and metastasis and discussed the concept of therapy-induced expression of AnxA6 as a novel mechanism for acquired resistance of TNBC to tyrosine kinase inhibitors." (PMID 34073560, 2021). "Cytotoxic chemotherapeutics can elicit tumour cells to secrete annexin A6‐enriched EVs and promote the expansion of Ly6C+CCR2+ monocytes on which the pro‐metastatic property of annexin A6‐enriched EVs relies." (PMID 33145869, 2021). "IHC was used to evaluate the levels of apoptosis and autophagy in the xenograft tumor, and we observed that rapamycin treatment greatly increased caspase 3 cleavage and LC3 level in wild‐type tumors than in ANXA6 knockdown tumors." (PMID 33135350, 2020). "Significant tumor suppression was observed in the rapamycin‐treated groups compared with the PBS‐treated groups, but the tumor suppressive effect was attenuated by ANXA6 knockdown." (PMID 33135350, 2020). "It has also been shown that the expression of AnxA6 and GRF2 are epigenetically modulated in some cancers, and that inhibition of Ca2+ signaling influences the expression of tumor suppressor genes via epigenetic mechanisms." (PMID 32298357, 2020). "It has been amply reported that AnxA6 plays a role in the progression of TNBC and other cancer types based on changes in the expression of the protein in various neoplasms." (PMID 32784650, 2020). "Targeting ANXA1 and ANXA6 is relevant because, where ANXA1 is downregulated/absent, ANXA6 expression can be restored in a compensatory manner, partially sustaining tumor progression." (PMID 41744829, 2026). "Our findings that detection of Ki67 and AnxA6 together with EpCAM for epithelial/proliferative cells and vimentin for mesenchymal-like/invasive cells can be used to identify these cell types in a typical TNBC tumor for rational treatment strategies." (PMID 41279138, 2025). "AnxA6 acts as a tumor suppressor through inhibiting EGFR/ERK pathway, therefore we would explore whether SUMOylation of AnxA6 is involved in EGFR/ERK signaling regulation." (PMID 37528485, 2023). "Thus, ANXA6 interacts with several proteins like p120 GAP, Raf1 and PKCalfa, downregulating this pathway, thereby acting as a tumor suppressor in several human cancers." (PMID 36247003, 2022). "Furthermore, when mimicking the three-dimensional complexity of the stromal tumour microenvironment, LDL-inducible A431 cell invasion was strongly reduced upon AnxA6 overexpression." (PMID 35022465, 2022). "Additionally, the levels of tumor-promoting genes (Lrp5, MMP9, Runx2, and Snail) were increased by TGFβ and CXCL5, while they were reduced by TPM4, ANXA6, and Trail." (PMID 34230453, 2021). "Additionally, proteins involved in the regulation of the cell cycle (e.g., ATM and STAT3), cell proliferation (e.g., LYN and SRRT), metabolism (e.g., GOT2, PPP1CA, and PYGB), and the regulation of Ca2+ flux (e.g., ANXA6 and CALM1) were also found phosphorylated in the tumor cells." (PMID 40129242, 2025).
tumor (continued). "Likewise, inhibiting the CD9-positive ANXA6-EVs could potentially reduce the stromal modification and PDAC tumor progression." (PMID 38542378, 2024). "Compared with nontumor tissues, ANXA6 expression was significantly decreased in tumor tissues." (PMID 33135350, 2020). "In the present study, we confirmed that ANXA6 expression was higher in KIRC tissues than that in normal tissues, but this expression was not related to the stage of the tumour." (PMID 39290334, 2022).